MET (MET proto-oncogene, receptor tyrosine kinase)
Diseases named in the same sentence as MET in open-access papers (continued):
Sharing a sentence is not in itself a finding about the gene and the disease.
colon carcinoma (continued). "In this study, we demonstrated that MET activation induced by cetuximab was responsible for cetuximab resistance in colon cancer cells, indicating the benefits of MET inhibition as a novel therapeutic strategy to overcome MET-driven resistance in the clinic." (PMID 24714091, 2014). "In this study, we demonstrated that MET activation induced by cetuximab was involved in resistance to cetuximab in colon cancer cells." (PMID 24714091, 2014). "While most of the specific amino acid mutations mirror what is seen on the COSMIC database, some unique colon cancer gene mutations were found, which include ABL1-F359V, AKT1-E17K, MET-R970C, and MET-T992I." (PMID 20233444, 2010). "Overexpression of Rab31 in cancer-associated fibroblasts (CAFs) enhances cell migration in an HGF/MET-dependent manner in colon cancer cells, indicating a key role for Rab31-expressed CAF in the colon cancer cell migration by mediating paracrine secretion of HGF." (PMID 38695990, 2024). "Here, we found that GALNT2 knockdown suppressed the activity of EGFR and MET in colon cancer cells." (PMID 36409270, 2023). "Consistently, LINE-1 hypomethylation caused by the inhibition of DNMTs in colon carcinoma cells or myeloid leukemia cells induces the expression of an irregular fusion transcript between an intronic LINE-1 element and the proto-oncogene MET (c-Met)." (PMID 35719395, 2022). "In addition, in order to assess the regulatory role of c-MET in the migration and metastasis of colon cancer cells, we performed a wound surface test and an infiltration test." (PMID 35874635, 2022). "In addition, the simultaneous inhibition of MET and Src demonstrated that the combination treatment reduced cell viability and increased the apoptosis rate in mutant and wild-type Ras colon cancer cells." (PMID 36430388, 2022). "Transwell experiments showed that c-MET was a metastatic factor in colon cancer because of the overexpression of c-MET leading to an increase invasion of colon cancer cells, while si-c-MET inhibited the invasion of colon cancer cells, which is with the opposite results (P < 0.01)." (PMID 35874635, 2022). "Subsequently, the function of c-MET was verified in colon cancer cells by a series of experiments." (PMID 35874635, 2022). "This study demonstrates the limited number of genetic MET aberrations present in a Northern Irish colon cancer cohort and identifies a cancer‐specific poor prognosis MET RNA/c‐MET protein subgroup that may be amenable to targeted therapy." (PMID 34428346, 2021). "Herein, the aim of the present study is to establish the relative incidence and prognosis of aberrant c‐MET expression patterns based on mRNA and protein analysis, relative to mutational status and MET amplification, using a stage II/III population‐representative colon cancer (CC) cohort." (PMID 34428346, 2021). "In the preclinical analysis included in the study, both MET tyrosine kinase inhibitor and an anti-MET monoclonal antibody inhibited the growth of a patient-derived colon cancer cell line harboring MET exon 14 deletion, thus suggesting its potential role as a predictive biomarker for MET inhibitors." (PMID 34943612, 2021). "Inhibition of the MET kinase activity by JNJ38877605 or inhibition of the biological activity of HGF by SRI31215, a novel small molecule inhibitor of pro-HGF activation, restored sensitivity of HGF-producing colon cancer cells to EGFR inhibition by blocking autocrine MET activation." (PMID 28420162, 2017). "HGF-producing colon cancer cells display autocrine activation of MET signaling." (PMID 28420162, 2017). "Furthermore, MACC1 has been found to stimulate proliferation, motility and invasion in colon cancer cells through transcriptionally upregulating c-MET." (PMID 23497677, 2013). "Mutations in ABL1 and MET, not previously identified in colon cancer, were identified, and 13 other genes were screened and found not to be mutated in hot spot locations." (PMID 20233444, 2010).
colon carcinoma (continued). "Indeed, the very oncogenic receptor tyrosine kinase MET was also shown to promote serpinE2 gene expression in a xenograft colon tumor model." (PMID 20942929, 2010). "Furthermore, we identified MET as a Wnt signalling target gene, indicating that the expression of Met in the majority of both hereditary as well as sporadic colon tumours is a consequence of active Wnt signalling." (PMID 15785735, 2005). "Although c-MET was regulated by miR-31 in DLD-1 colon cancer cells, we could not identify a significant statistical association of hsa-miR-31-5p expression and c-MET immunopositivity in the patients’ tumor tissue samples." (PMID 29463215, 2018). "Finally, we demonstrated that miR-31 down-regulated c-MET in DLD-1 colon cancer cells." (PMID 29463215, 2018). "We thus selected c-MET to test whether miR-31 is active in colon cancer cells." (PMID 29463215, 2018). "Here we report that MET p.T992I, a non-synonymous change suggested to have oncogenic potential, is present in the germline DNA of 5.2% of this cohort and this same change is confirmed in a second familial colon cancer cohort with two affected first degree relatives at a frequency of 4.1%." (PMID 21970370, 2011). "Metastasis-associated in colon cancer 1 (MACC1) was original identified as a transcription factor of c-MET, which activates the HGF/Met signal pathway and induces colon cancer cell metastasis and invasion." (PMID 39695175, 2024). "With further exploration, we proved that c-MET is downstream of MACC1 in colon cancer and that overexpression of c-MET in colon cancer enhances cell proliferation and migration capability." (PMID 35874635, 2022). "In an in vitro EdU assay, c-MET overexpression increased the proliferation rate of colon cancer cells, while si-c-MET suppressed the colon cancer cell proliferation (P < 0.01)." (PMID 35874635, 2022). "The exploration of the MACC1/HGF/c-MET pathway in colon cancer provides favorable evidence for drug targeting of MACC1 and regulation of MACC1/HGF/c-MET in colon cancer therapy." (PMID 35874635, 2022). "MET and its ligand HGF have also been shown to interact with Wnt signaling to maintain stemness in colon cancer cells." (PMID 34069138, 2021). "H3K36me2, expressions of multiple oncogenes (ADAM9, EGFR, Sox2, Bcl-2, SYK, and MET) and Akt activation were significantly decreased after NSD2 silencing or knockout in primary colon cancer cells." (PMID 34671018, 2021). "In colon cancer, HGF secreted by fibroblasts has been shown to drive colon cancer cell proliferation through c-MET dependent signalling." (PMID 33271944, 2020). "Dual inhibition of SRC and MET led to synergistic cytotoxic effects in HNSCC models, and this combination targeting has also emerged as a promising therapeutic strategy for colon cancer." (PMID 31731442, 2019). "Meaningfully, SRI 31215 overcomes autocrine HGF/MET signaling-mediated the primary resistance to EGFR inhibitors (cetuximab and panitumumab) in colon cancer cells." (PMID 30360560, 2018). "We used the MC38-CEA murine colon carcinoma cell line which expresses both VEGFR2 and MET (inset), in addition to the human carcinoembryonic antigen (CEA), to examine the in vitro immunomodulatory effects and in vivo antitumor effects of cabozantinib." (PMID 25388653, 2014). "Arm-level gains of c-MET were positively correlated with CD8+ T cell, B cell, neutrophil, and dendritic cell infiltration in colon cancer and dendritic cells infiltration in READ, while deep deletions of c-MET were associated with CD8+ T cell and neutrophil infiltration of tumors in READ." (PMID 34512327, 2021). "SPRY2 is known to positively regulate MET levels in colon carcinoma, although it is unclear whether SPRY2 induces MET transcriptional activation or reduces MET degradation." (PMID 29445192, 2018).
colon carcinoma (continued). "We demonstrated previously that SRI31215 effectively inhibits HGF-dependent MET activation, proliferation, epithelial-mesenchymal transition and migration of cancer cells and overcomes fibroblast-mediated resistance to EGFR inhibitors in colon cancer cells." (PMID 28968967, 2017). "Since MET levels are a negative prognostic indicator for colon cancer, these findings suggest an oncogenic role for L1-MET." (PMID 27980689, 2016). "We applied a limited candidate gene approach (EGFR, HGF ad MET by immunohistochemistry), array CGH, and genomic sequencing to compare CB42 to other propagation-incapable, β-Catenin-driven primary colon tumors to identify a series of candidate genes that correlated with propagation/metastasis." (PMID 25162504, 2014). "Similarly, in acquired cetuximab-resistant colon cancer cells, overexpression of TGF-α induced the EGFR-MET interaction with subsequent MET phosphorylation, which contributed to cetuximab resistance." (PMID 24714091, 2014). "Previous studies have shown that MACC1 acts as a transcription activator for c-MET and as a key regulator of HGF-c-MET signaling pathway in colon cancer, promoting proliferation, invasion and HGF-induced scattering of colon cancer cells and xenograft growth and metastasis in vivo." (PMID 23497677, 2013). "Colon cancer cell growth inhibition was accompanied by downregulation of Sp1, Sp3 and Sp4 proteins and decreased expression of Sp-regulated gene products including bcl-2, survivin, VEGF, VEGFR1, cyclin D1, c-MET and p65 (NFκB)." (PMID 23110215, 2012). "First, the SP1 motif is necessary for MACC1-mediated MET expression in colon cancer cells, which suggests that MACC1 regulation of MET requires involvement with SP1; in terms of this, MACC1 may not interact with SP1 and therefore does not regulate pancreatic cancer metastasis via the MET pathway." (PMID 36333284, 2022). "Then, we identified the MACC1/HGF/c-MET axis in colon cancer and tried to explore whether this axis could interfere with colon cancer invasion and metastasis by regulating MACC1 or by blocking the expression of downstream c-MET." (PMID 35874635, 2022). "Thus, our results suggested that MET activation induced by cetuximab conferred resistance to cetuximab in non-MET-amplified colon cancer cells, identifying a subset of colon cancer patients who develop cetuximab resistance in the absence of MET amplification." (PMID 24714091, 2014). "Additionally, we further confirmed that the interaction between MET and SRC and the formation of MET/SRC/EGFR complex contributed to constitutive MET activation, providing a rationale for combinatorial inhibition of EGFR and MET or EGFR and SRC in therapy targeting colon cancer." (PMID 24714091, 2014). "Next, the expression of phosphorylated and total MET and SRC was evaluated by Western blotting; the variable expression of these proteins did not correlate with cetuximab response in colon cancer cells." (PMID 24714091, 2014).
ovarian carcinoma (119 papers, 2007 to 2026). A malignant neoplasm originating from the surface ovarian epithelium. "Increased expression of CD24 and MET, markers for cancer stem‐like cells (CSCs), are each associated with ovarian cancer severity." (PMID 38030594, 2024). "The coexpression of MET and plexin-B1, the receptor of Sema4D, was associated with advanced-stage breast and ovarian carcinoma as indicated in MET/plexin-B1 double-positive tumors." (PMID 39742369, 2024). "In EOC, MET is overexpressed in 7–27% of the population and is associated with progression and adverse outcomes of ovarian cancer." (PMID 32295618, 2020). "In previous studies, c-MET overexpression in ovarian carcinoma has been associated with advanced tumor stage, and the knockdown of endogenous c-MET expression using siRNA has been found to greatly reduce the invasive ability of the cells." (PMID 25009663, 2014). "In ovarian cancer, overexpression of MET was associated with poor prognosis where tumors with overexpression of MET protein had lower survival rate in comparison to those with low MET expression (17 months versus 32 months)." (PMID 23320251, 2012). "In addition, analyses using KM plotter and ROC plotter presented that the overexpression of CD24 or MET in ovarian cancer patients was associated with resistance to platinum‐based chemotherapy." (PMID 38030594, 2024). "In ovarian cancer, MET expression was associated with proliferation and lymph node metastasis." (PMID 38030594, 2024). "Furthermore, in a study of patients with ovarian cancer, c-MET expression was linked to a clinicopathological characteristic associated with poor prognosis." (PMID 35630066, 2022). "High expression of c-MET in ovarian cancer has been associated with poor survival and the use of c-MET inhibitors could enhance the effects of platinum-taxane therapy." (PMID 26964739, 2016). "It has been reported that MET inhibition in osteosarcoma cancer is associated with higher tumor aggressive behavior and resistance to cisplatin therapy, and overexpression of MET enhances survival of ovarian cancer cells and increased resistance to cisplatin." (PMID 27014910, 2016). "However, one thing remained certain, that the involvement of HGF/MET pathway in promoting cell proliferation and dissemination in ovarian cancer was highly associated with the expression of high levels of the HGF receptor." (PMID 23320251, 2012). "However, as with other cancer types, multiple prior investigations have shown that cancer growth is linked to an abnormally active HGF/c-MET axis in subsets of all four major histocytes in ovarian cancer (high-grade serous, clear cell, mucinous, and endometroid)." (PMID 35630066, 2022). "Using pooled human and murine ovarian cancer sera, we observed that pharmacological inhibition of c-MET (AMG337) and IGF-1R (PPP) significantly attenuated AIG colony formation." (PMID 40804939, 2025). "According to our results, CD24 expression induced the downregulation of miR‐181a, contributing to MET overexpression in serous types of ovarian cancer cell lines, OV90 and SK‐OV‐3 cells." (PMID 38030594, 2024). "The Fer driven metastatic dissemination of ovarian cancer cells depends on the Fer mediated phosphorylation and activation of the Hepatocytes Growth Factor Receptor (HGFR/MET) in a ligand-independent manner." (PMID 36982326, 2023). "We present the findings of clinical studies using small chemicals or antibodies targeting HGF/c-MET signaling in various cancer types, particularly in ovarian cancer." (PMID 35630066, 2022). "In this review, we discuss the role of the HGF/c-MET axis in ovarian cancer metastasis and prognosis, as well as other cancer types." (PMID 35630066, 2022). "Li and collaborators described an elevated expression of c-MET in cisplatin-resistant cell lines as compared to parental cell lines of ovarian cancer cells." (PMID 35406455, 2022).
ovarian carcinoma (continued). "Several studies found that CAF-derived HGF increased chemoresistance in ovarian cancer cells in vitro and in vivo via upregulating MET/PI3K/Akt signaling." (PMID 35630066, 2022). "Studies with the multi-target MET inhibitor cabozantinib, which was discovered and developed by Exelixis, have shown significant activity in ovarian cancer." (PMID 35630066, 2022). "We took advantage of our previous studies on ovarian cancer, which demonstrated the prognostic relevance of both sHGF levels and the soluble ectodomain of its receptor c-MET (sMET)." (PMID 36338759, 2022). "Another study examined the effect of crizotinib in 119 human ovarian cancer cells with c-MET overexpression, similarly concluded the elevated activity of crizotinib in ovarian cancer cells expressing high c-MET." (PMID 31766284, 2019). "Nevertheless, these c-MET inhibitors show promising results against ovarian cancer cells, however, the response in long-term use in treatment requires further investigation." (PMID 31766284, 2019). "BMS-777607 is another small molecule c-MET inhibitor which has shown promising anti-tumorigenic activity against prostate cancer metastasis, as well as being studied in ovarian cancer cells." (PMID 31766284, 2019). "Exposure of sarcoma and PDX ovarian carcinoma cells to [pazopanib + entinostat] caused a prolonged activation of ERBB1 and transient/prolonged activations of ERBB2, c-KIT, and c-MET, in a cell-specific fashion." (PMID 31380285, 2019). "In conclusion, the present study demonstrated that HGF was blocked by YYB-101, inhibiting the growth of ovarian cancer cells through the signaling pathway mediated by c-MET, the target receptor for HGF." (PMID 31355133, 2019). "In several studies, c-MET inhibitors such as crizotinib and foretinib effectively inhibited the development and metastasis of ovarian cancer in animal models." (PMID 31355133, 2019). "c-MET expression is observed in 70% of ovarian carcinomas, 30% of which present with overexpression." (PMID 31857852, 2019). "At the cut of value of above 5% of the tumour cells with positive immunostaining, the expression of c-MET was detected in 13/60 ovarian cancer cases (21.7%) with its cellular location all being cytoplasmic." (PMID 29731973, 2018). "Altered gene expression signature also indicated the reduced c-MET/EGFR signaling in NRF2-silenced ovarian cancer cells." (PMID 29291022, 2017). "Expression levels of c-MET in the epithelial ovarian cancers (EOCs) and normal ovarian tissues were evaluated using real-time PCR." (PMID 27917934, 2016). "We evaluated expression of c-MET and phosphorylated c-MET (p-c-MET) in ovarian cancer cell lines using Western blot." (PMID 27917934, 2016). "We have provided evidence of the potential efficacy of the c-MET inhibitor INC280 to inhibit many of the metastatic behaviours exhibited by ovarian cancer cells in vitro and ex vivo." (PMID 26138303, 2015). "In silico analyses indicated that MET is one of the target genes for miR-199a-3p; subsequently, miR-199a-3p expression was found to be inversely correlated with c-Met expression in ovarian cancer." (PMID 25839163, 2015). "In tumors, however, including ovarian cancer, c-MET overexpression and paralleled hyperactivation correlates with poor prognosis by triggering tumor growth, metastasis and angiogenesis." (PMID 26436697, 2015). "We have reported here the first investigations of the small molecule c-MET inhibitor INC280 in well characterized ovarian cancer cell line models, as well as normal human ovarian surface epithelium cells." (PMID 26138303, 2015). "As a result, the current study investigated the potential association between c-MET and MACC1 in ovarian cancer." (PMID 25009663, 2014). "These experiments were performed in OVCA429 ovarian cancer cells because of their high MET expression as determined by Western blot." (PMID 24265843, 2013).